LNCPOIR (lncRNA periodontal mesenchymal stem cell osteogenesis related)
Synonyms: POIR; lncRNA-POIR
Gene: Long non-coding RNA gene on chromosome 6 (114,441,273 to 114,581,005, reverse strand). Ensembl gene ENSG00000232395.
Diseases named in the same sentence as LNCPOIR in open-access papers:
LNCPOIR is named in the same sentence as 1 disease in open-access papers, as found by Europe PMC text mining. Sharing a sentence is not in itself a finding about the gene and the disease.
LNCPOIR shares sentences with these, for which no sentence is quoted: periodontitis (6 papers).